VASP (vasodilator stimulated phosphoprotein)
Diseases named in the same sentence as VASP in open-access papers (continued):
Sharing a sentence is not in itself a finding about the gene and the disease.
Stroke (5 papers, 2010 to 2023). Sudden impairment of blood flow to a part of the brain due to occlusion or rupture of an artery to the brain. "Next we sought to elucidate the underlying mechanisms of this VASP-specific stroke protection." (PMID 21151938, 2010). "VASP is an actin regulatory protein implicated in platelet adhesion while ITGA2B encodes aIIb and is an important gene associated with COVID-19-related stroke." (PMID 36859478, 2023). "Further analysis is required for better understanding of the role of VASP in platelet function and thrombosis in other contexts, such as stroke and balloon injury, in combination with other experimental approaches, including morphological and histological analysis of platelets and thrombi." (PMID 29967338, 2018). "Interference with VASP or VASP-dependent signalling pathways could become a promising strategy to treat excessive brain edema in stroke and possibly other neurological diseases afflicted with severe BBB disruption." (PMID 21151938, 2010). "Therefore, we injected mice the vascular tracer Evan's Blue to investigate whether VASP is also involved in stroke-induced BBB damage and edema formation." (PMID 21151938, 2010). "After multivariate adjustment for previous percutaneous coronary intervention, previous stroke, MPV, hsCRP, left ventricular ejection fraction, and aspartate transaminase, dual antiplatelet therapy remained independently significant in predicting HPR in the LTA and VASP assay." (PMID 34876147, 2021).
dilated cardiomyopathy (4 papers, 2010 to 2023). Cardiomyopathy which is characterized by dilation and contractile dysfunction of the left and right ventricles. "Left-ventricular performance was increasingly impaired in adult VASP-, Mena-, and Mena/VASP double deficient mice but only the double-deficient animals developed dilated cardiomyopathy." (PMID 37443774, 2023). "Left-ventricular performance was increasingly impaired in adult VASP-, Mena-, and Mena/VASP double-deficient mice and only the double-deficient animals developed dilated cardiomyopathy." (PMID 23937664, 2013). "Conversely, Mena/VASP deficiency results in disrupted β-actin assembly, Z- and intercalated disc malformation, and induces dilated cardiomyopathy and conduction abnormalities." (PMID 23937664, 2013). "Also, combined disruption of the localization of ENAH and VASP in cardiac intercalated disks causes dilated cardiomyopathy and early postnatal lethality, whereas VASP knock-out mice show no cardiac abnormalities." (PMID 20565797, 2010). "Transgenic mice showed displacement of both VASP and Mena from intercalated disks and developed dilated cardiomyopathy and myocyte hypertrophy." (PMID 37443774, 2023).
endothelial dysfunction (4 papers, 2018 to 2024). In vascular diseases, endothelial dysfunction is a systemic pathological state of the endothelium (the inner lining of blood vessels) and can be broadly defined as an imbalance between vasodilating and vasoconstricting substances produced by (or acting on) the endothelium. "In order to examine whether NADPH oxidase–driven ROS production is involved in endothelial dysfunction induced by AngII, we measured the relaxation to ACh in aorta and the phosphorylation of VASP at Ser239 by immunofluorescence in RAECs incubated with the specific pan-NOX inhibitor VAS2870." (PMID 32372967, 2020). "VASP is phosphorylated by PKG at serine 239 and has previously been identified as a sensitive indicator of impaired NO-cGMP signaling and endothelial dysfunction." (PMID 39485297, 2024). "Interestingly, VAS2870 restored ACh-induced relaxation and p-VASP- Ser239 level in AngII-treated aorta and RAECs, respectively, confirming the critical involvement of NADPH oxidase in AngII-induced endothelial dysfunction." (PMID 32372967, 2020).
lung adenocarcinoma (4 papers, 2015 to 2023). A carcinoma that arises from the lung and is characterized by the presence of malignant glandular epithelial cells. "Elevated levels of the actin-associated protein VASP in lung adenocarcinoma correlate with the degree of de-differentiation and poor pathological stage." (PMID 27322681, 2016). "Studies have shown that the expression level of VASP in lung adenocarcinoma tissues is significantly higher than that in normal tissues, and the expression level of VASP is correlated with tumor differentiation." (PMID 31754343, 2019). "Another study on ICRN indicated that it could suppress the adhesion of lung adenocarcinoma by acting on vasodilator phosphoprotein (VASP), which is important in cell migration along with tumor metastasis." (PMID 36662090, 2023). "Only in lung adenocarcinomas increased VASP expression was described when compared to normal epithelium." (PMID 26336132, 2015).
atherosclerosis (3 papers, 2016 to 2018). A disease characterized by the build-up of fatty material and calcium deposition in the arterial wall resulting in partial or complete occlusion of the arterial lumen. "VASP dysfunction has been linked to many diseases including cancer, atherosclerosis and thrombosis." (PMID 27711191, 2016). "These discrepancies in VASP-mediated platelet phenotypes between previous findings and our findings might be due to species differences (mice vs. rats) and/or subjected thrombotic stimuli (I/R or atherosclerosis vs. FeCl3)." (PMID 29967338, 2018).
ischemic stroke (3 papers, 2010 to 2023). A stroke disorder caused by obstruction of blood flow to the brain, due to thrombotic (local blood clot formation) or embolic (due to a blood clot or other material traveling from another site) event. "Bradykinin (an inflammatory peptide hormone)-induced edema formation was significantly increased in VASP-deficient mice and VASP-deficiency also increased blood brain barrier damage and edema formation after ischemic stroke." (PMID 37443774, 2023). "Because HIF is also strongly induced in the murine brain after tMCAO, HIF-dependent degradation of VASP could also be functionally relevant for edema formation in ischemic stroke in vivo." (PMID 21151938, 2010). "We here confirm and further extend these findings by demonstrating that VASP also prevents BBB damage and edema formation in the brain after tMCAO in mice, a well established in vivo model of ischemic stroke." (PMID 21151938, 2010).
lipoma (3 papers, 2008 to 2020). A benign, usually painless, well-circumscribed lipomatous tumor composed of adipose tissue. "At focal adhesions the C-terminal SH3 domain of LASP-1 is involved in protein-protein interactions through binding to proline-rich sequences, specifically with palladin, lipoma preferred partner (LPP), Prointerleukin-16 (Pro-IL-16), vasodilator stimulated phosphoprotein (VASP) and zyxin." (PMID 18419822, 2008).
Obesity (3 papers, 2018 to 2022). Accumulation of substantial excess body fat. "Methylation loci associated with obesity (AEBP2), calcium signaling (CAPNS1), insulin signaling (INSR, PTPRN2, RPTOR) and vasodilation (VASP) also appeared to be epigenome-wide significant." (PMID 29692868, 2018). "In addition to the findings of these immune-regulatory genes, many other top associations have been implicated in obesity (AEBP2) (FDR < 0.10), calcium signaling (CAPNS1), insulin signaling (INSR, PTPRN2, RPTOR), and vasodilation (VASP)." (PMID 29692868, 2018). "Instead, our screen suggests that different nearby cis gene may be more fruitful for further functional follow up for obesity, namely ZCCHC8, VPS33A, RSRC2; SPDEF, NUDT3; SETD1, VKORC1; SGSM2, SRR; VASP, SIX5; OTX1; BANK1; ARIH1; ELL; CHST8, respectively." (PMID 29608557, 2018).
acute coronary syndrome (2 papers, 2015 to 2020). Signs and symptoms related to acute ischemia of the myocardium secondary to coronary artery disease. "Among 444 prasugrel-treated patients with acute coronary syndrome undergoing PCI and assessed 2 to 4 weeks after hospital discharge, patients with DM had higher vasodilator-stimulated phosphoprotein (VASP) index than non-DM patients, but this effect was not present in multivariate analysis." (PMID 26025572, 2015).
Alzheimer disease (2 papers, 2021 to 2025). A progressive, neurodegenerative disease characterized by loss of function and death of nerve cells in several areas of the brain leading to loss of cognitive function such as memory and language. "Surveying the 4158 TMEM119+ cells captured from cortical tissue sections of six subjects obtained from Rush Alzheimer’s Disease Center, we find that TMEM119 + VASP + microglia are less ramified than TMEM119 + VASP− cells (P = 3 × 10-8, β = −0.26)." (PMID 33446646, 2021).
cardiomyopathies (2 papers, 2010 to 2023). "Changes in VASP activity have been linked to cardiomyopathies." (PMID 36936778, 2023). "Dominant negative inhibition of both Enah and VASP results in cardiomyopathy." (PMID 20886071, 2010).
colorectal cancer (2 papers, 2018 to 2019). A primary or metastatic malignant neoplasm that affects the colon or rectum. "In patient-derived samples, VASP is upregulated in 53 of 63 colorectal cancers and 43 of 53 pancreatic ductal adenocarcinomas and high VASP levels correlate with liver metastasis and reduced patient survival." (PMID 29872721, 2018). "Interestingly, colorectal cancer cells have the ability to form locomotory and invasive filopodia that promote invasion and metastasis, and this is suppressed by the phosphorylation of Vasodilator-Stimulated Phosphoprotein (VASP)." (PMID 31718063, 2019).
coronary artery disease (2 papers, 2012 to 2022). "Accordingly, washed platelets isolated from coronary artery disease patients show increased levels of phosphorylated VASP compared with control group, which is further enhanced by ODQ." (PMID 23144808, 2012).
gastric adenocarcinoma (2 papers, 2016 to 2019). "Studies on the gastric pathogen H. pylori have shown vasodilator-stimulated phosphoprotein (VASP) to be a target protein of this Helicobacter species, with VASP mediating elongation of gastric adenocarcinoma cells." (PMID 27045955, 2016).
glioblastoma (2 papers, 2009 to 2021). The most malignant astrocytic tumor (WHO grade IV). "Consequently, Lpd and RICTOR may interconnect with the Ena/VASP or Scar/WAVE complex to facilitate invasion in glioblastoma." (PMID 34771501, 2021).
heart failure (2 papers, 2012 to 2015). Inability of the heart to pump blood at an adequate rate to meet tissue metabolic requirements. "Since augmented adrenergic activity is one of the features of heart failure, we determined phosphorylation of vasodilator-stimulated phosphoprotein (VASP) at Ser157, a protein kianse A phosphorylation site, in the myocardium." (PMID 26259714, 2015). "The mammalian homolog of Drosophila enabled (Enah) Mena is a member of the enabled/vasodilator-stimulated phosphoprotein (Ena/VASP) family of actin regulatory proteins that act as critical regulators of actin assembly and cell motility with increased levels in heart failure." (PMID 22558231, 2012).
Insulin resistance (2 papers, 2018 to 2020). Increased resistance towards insulin, that is, diminished effectiveness of insulin in reducing blood glucose levels. "The VASP-STAT axis has been described in mice with a myeloid-specific deficiency of VASP, mice were prone to hepatic inflammation and insulin resistance in a STAT6-dependent manner." (PMID 32140136, 2020).
liver cancer (2 papers, 2017 to 2022). An epithelial or non-epithelial malignant neoplasm that arises from the liver. "CAP2 was coexpressed with TP53BP2, ENA/VASP in the liver cancer, and CFL1, CFL2, DSTN, ACTB, ACTG1, and ROBO1." (PMID 28423713, 2017). "CAP2 was coexpressed with TP53BP2 and ENA/VASP in liver cancer." (PMID 28423713, 2017). "The activation of HIF-1 can overexpress VASP, and VASP changes the EMT phenotype by activating AKT and ERK signals and promotes the metastasis of liver cancer in vivo and in vitro." (PMID 36387147, 2022).
lung carcinoma (2 papers, 2021 to 2023). "Research related to ABPs and lung cancer has mainly focused on twinfilin-1 (TWF1) and fascin-1 and on the relationships between VASP, profilin-1, and cofilin-1." (PMID 34194957, 2021).
myocardial infarction (2 papers, 2016 to 2020). Gross necrosis of the myocardium, as a result of interruption of the blood supply to the area, as in coronary thrombosis. "The primary endpoint is platelet reactivity index measured by vasodilator-stimulated phosphoprotein phosphorylation 2 hours after the LD, and the secondary endpoints include occurrence of periprocedural myocardial infarction and bleeding events." (PMID 27258504, 2016).
myocardial ischemia (2 papers, 2011 to 2012). A disorder of cardiac function caused by insufficient blood flow to the muscle tissue of the heart. "With these findings we were able to confirm the findings of a previous study demonstrating the role of VASP during myocardial ischemia-reperfusion." (PMID 22216296, 2011).
ovarian carcinoma (2 papers, 2019 to 2021). A malignant neoplasm originating from the surface ovarian epithelium. "VASP has also been previously reported to be functionally regulated by PKG1α and involved in chemoresistance, cell migration and invasion in ovarian cancer." (PMID 32123828, 2019). "In addition, the phosphorylation of VASP was reported to drive tumor cell migration and platinum resistance in ovarian cancer." (PMID 33385064, 2021). "Most metastatic‐related proteins (eg, coronin‐1A, TPT‐1, VASP, HSP90α, cofilin, and Arp 2/3) were identified in both CAB and CAO patients, suggesting their association with organotropism of metastatic breast and ovarian cancers." (PMID 32123828, 2019). "Additionally, proteins namely VASP, coronin‐1A, stathmin, and suprabasin were confidently identified in ovarian chemotherapy subjects, possibly in response to combined paclitaxel and carboplatin drug therapy to ovarian cancer." (PMID 32123828, 2019).
Achalasia (1 paper, 2023). A disorder of esophageal motility characterized by the inability of the lower esophageal sphincter to relax during swallowing and by inadequate or lacking peristalsis in the lower half of the body of the esophagus. "In this study, 164 serum proteins changed significantly in achalasia patients among which the most significantly changed proteins were profilin-1, immunoglobulin heavy variable 3–9, transgelin-2, vasodilator-stimulated phosphoprotein, and galectin-10 (all were upregulated)." (PMID 37324545, 2023).
bone cancer (1 paper, 2019). A primary or metastatic malignant neoplasm affecting the bone or articular cartilage. "First, through FRAP-experiments we examined the binding dynamics of fluorescently-labelled paxillin, vinculin, VASP and zyxin at FAs in two different cell-types from two different species; U2OS cells, a human bone cancer cell line, and MDCK dog kidney cells." (PMID 31320676, 2019).
brain infarct (1 paper, 2015). "In CIR rats, SCU preincubations could significantly decrease brain infarct size, vascular tension, and the values of BA cumulative-response curves of ACh, EC50, and Emax and increase protein level of p-VASP in HR BA." (PMID 26557858, 2015).
Cachexia (1 paper, 2019). Severe weight loss, wasting of muscle, loss of appetite, and general debility related to a chronic disease. "As the tumor burden increased, the body weight of the mice decreased significantly, showing a cachexia state and knockdown of VASP can significantly improve the living conditions of tumor-bearing mice." (PMID 31754343, 2019).
Cerebral ischemia (1 paper, 2010). Restriction of arterial blood supply to the brain associated with insufficient oxygenation to support the metabolic requirements of the tissue. "Taken together, our study indentifies VASP as critical regulator of BBB maintenance and fluid hemostasis during cerebral ischemia." (PMID 21151938, 2010).
cerebrovascular diseases (1 paper, 2015). "This study advances not only our understanding about the regulation of VASP and PKG-I, but also a mechanism underlying the beneficial effects of SCU in treating cerebrovascular diseases." (PMID 26557858, 2015).
chronic myeloid leukemia (1 paper, 2016). "VASP interacts with ABL (breakpoint cluster region-abelson) and is a substrate of the BcrAbl oncoprotein which drives oncogenesis in patients with chronic myeloid leukemia (CML) due to a constitutive activation of tyrosine kinase activity." (PMID 27379155, 2016).
cognitive decline (1 paper, 2021). "At the single gene level, VASP RNA expression in cortical tissue is also strongly associated with activated microglial counts and cognitive decline, as well as Tau (P = 0.0007, β = 0.052)." (PMID 33446646, 2021).
diarrheal disease (1 paper, 2020). The condition of having at least three loose or liquid bowel movements each day. "Contrary, during infections with the intracellular bacterial pathogens Shigella spp., which cause diarrheal disease in humans, VASP and the related protein Ena/VASP-like (EVL) limit bacterial spread." (PMID 32997728, 2020).
ductal carcinoma in situ (1 paper, 2015). "Immunohistochemical (DAB staining) analysis of progression tissue microarrays (TMAs) including normal breast tissue, ductal carcinoma in situ (DCIS), 3 groups of invasive ductal carcinomas (ER positive; HER2 positive; or TN) indicated that levels of total VASP are not indicative for progression." (PMID 26336132, 2015).
esophageal cancer (1 paper, 2024). A primary or metastatic malignant neoplasm involving the esophagus. "Furthermore, by triggering regional PKA expression and encouraging VASP phosphorylation at Ser239, the deletion of LAMP3 significantly reduced the motility and spread of esophageal cancer cells." (PMID 38922530, 2024).
fibrosis (1 paper, 2018). the formation of excess fibrous connective tissue in an organ or tissue in a reparative or reactive process. "It was also shown that VASP family appear to modulate diverse cellular responses as migration and cell–cell junctions, as TAC procedure increases VASP expression and results in hyperthrophic remodeling, while cardiac fibrosis and hypertrophy markers are elevated in VASP−/− knockout mice." (PMID 30249014, 2018).
focal segmental glomerulosclerosis (1 paper, 2022). A renal disorder characterized by sclerotic lesions in the glomeruli. "It has been shown that VASP phosphorylation can increase podocyte motility and act as a biomarker for disease activity measurement in focal segmental glomerulosclerosis." (PMID 36309313, 2022).
hemolysis (1 paper, 2024). Disruption of the integrity of the erythrocyte membrane causing release of hemoglobin. "Our study is the first to show that intravascular hemolysis promotes voiding dysfunction correlated with alterations in the NO signaling pathway in the bladder, as evidenced by reduced levels of p-eNOS (Ser-1177), nNOS (Ser-1417), and p-VASP (Ser-239)." (PMID 39100273, 2024).
hepatic (1 paper, 2011). "Phosphorylation of VASP on Ser153 through Prostaglandin E1 or on Ser235 through atrial natriuretic peptide resulted in a significant reduction of hepatic IR injury." (PMID 22216296, 2011).
IgA nephropathy (1 paper, 2023). "Significant increases in the glomerular phosphorylation of VASP were seen in patients with minimal change disease and FSGS (pretransplant) compared with those with a noncirculating factor disease, IgA nephropathy." (PMID 36940798, 2023).
invasive ductal carcinomas (1 paper, 2015). "Similarly, the expression levels of PKD2, the kinase that phosphorylates VASP at this site, are decreased in invasive ductal carcinoma samples of all three groups." (PMID 26336132, 2015).
kidney damage (1 paper, 2022). "Since most SLE patients also have kidney damage at different severities, exploring the function of VASP S305 in SLE activity may also be worthwhile." (PMID 36309313, 2022).